IL10 (interleukin 10)
Diseases named in the same sentence as IL10 in open-access papers (continued):
Sharing a sentence is not in itself a finding about the gene and the disease.
tumor (continued). "In detail, STAT3, activated by cytokines such as IL‐6 and IL‐10 alongside growth factors including epidermal and fibroblast, mediates JAK/STAT signaling, a pathway critical for tumor progression and chemoresistance." (PMID 41509196, 2026). "Inflammatory cancer-associated fibroblasts (iCAFs) induced by FGF19 can secrete immunosuppressive factors such as interleukin-10 (IL-10) and transforming growth factor-β (TGF-β), which dampen anti-tumor immune responses." (PMID 41328353, 2026). "In tumor-bearing mice, antitumor efficacy, serum cytokines (TNF-α, IFN-γ, IL-6, IL-2, IL-10), and hematological indices were evaluated." (PMID 41965546, 2026). "Among these, interleukins such as IL-6, IL-8, and IL-10, along with chemokine axes including CXCL12-CXCR4 and CCL21-CCR7, are critical drivers of tumor progression and resistance to immunotherapy." (PMID 41884817, 2026). "Regulatory B cells (Bregs) are integral to the tumor microenvironment (TME) and influence immune responses through the secretion of immunosuppressive cytokines such as IL-10, IL-35, and TGF-β." (PMID 41614936, 2026). "These cells contribute to matrix remodeling, angiogenesis, and extracellular matrix reconstruction by secreting IL‐6, IL‐10, TGF‐β, and matrix metalloproteinases, thereby supporting tumor cell migration, peritoneal implantation, and metastasis." (PMID 41426206, 2026). "RT-qPCR analysis demonstrated upregulation of anti-tumor inflammatory cytokines (IL-6, TNF-α, iNOS) and concurrent downregulation of pro-tumor factors (IL-4, IL-10), confirming successful M2 to M1 phenotype conversion with efficacy comparable to LPS treatment." (PMID 41560805, 2026). "Regulatory B cells (Bregs) contribute to immune tolerance by inducing regulatory T cells (Tregs) and shaping the suppressive tumor microenvironment (TME) via the secretion of immunosuppressive cytokines (TGFβ and IL-10)." (PMID 41792971, 2026). "They activate the CSF1/CSF1R and IL‐10/STAT3 pathways, induce T‐cell exhaustion and metastatic phenotype switching, promote tumor infiltration and metastasis, and substantially shorten disease‐free and overall survival." (PMID 41426206, 2026). "Conversely, M2 phenotype macrophages, induced by TGF-β, IL-4, IL-10, IL-13, colony-stimulating factor-1 (CSF-1), and C-C motif chemokine ligand 2 (CCL2), exert anti-inflammatory and tumor-supportive effects." (PMID 41590379, 2026). "Conversely, chronic or dysregulated PRR signaling, often resulting from dysbiosis, can promote M2-like polarization through IL-10 and TGF-β production, contributing to immunosuppression and tumor progression." (PMID 41597210, 2026). "Tumor and stromal cells in the TME frequently produce Th2-type and immunosuppressive cytokines, such as IL-4, IL-13, IL-10, and TGF-β, which push macrophages toward an M2 state." (PMID 41597210, 2026). "In vitro assays confirmed that endothelial cells were educated by SLC1A3hi tumor cells that undergo malignant transition, drastically upregulating immune-suppressive factors, including CD274, TGFB1, IL10, and IDO1." (PMID 42112375, 2026). "Diagnostic approaches evolved from PET/CT-guided biopsy to a combination of serum interleukin-10 (IL-10, cut-off 95.65 pg/mL), random skin biopsy (RSB), and circulating tumor DNA (ctDNA) profiling." (PMID 41673727, 2026). "STT3A overexpression promoted tumor growth, increased TGF-β1 and IL-10 levels, and enhanced pulmonary metastasis, all of which were significantly reversed by DT treatment." (PMID 41493695, 2026). "They secrete high levels of anti-inflammatory and pro-fibrotic factors (e.g., IL-10 and TGF-β) and also express enzymes like arginase-1 (Arg1) that drive polyamine production for tissue repair and tumor growth." (PMID 41597210, 2026). "By contrast, 3D-primed ADSCs preserved organoid structure but markedly enhanced tumor cell migration through soluble factors, accompanied by increased IL-6 and TNF-α and reduced IL-10 secretion during co-culture." (PMID 41681933, 2026).
tumor (continued). "Tumor recognition by CAR T cells induces IFN‐γ and other cytokines, activating monocytes/macrophages → this amplifies inflammation through IL‐6, IL‐1, IL‐10, and TNF." (PMID 41207679, 2026). "These components not only facilitate intercellular tumour communication but also exert systemic effects through molecules such as TNF-α (Tumour Necrosis Factor), TGF-β (Transforming Growth Factor), IL-6, IL-10, and others." (PMID 41009413, 2025). "For example, miR-214 is secreted by tumor cells and delivered to Tregs via microvesicles, where it downregulates PTEN to promote Treg expansion and secretion of IL-10, enhances immune suppression and tumor growth." (PMID 40647470, 2025). "This change is associated with the immunosuppression and angiogenesis promoted by M2 macrophages, which support the survival and expansion of cancer cells by releasing anti-inflammatory factors such as IL-10 and TGF-β and pro-tumor factors." (PMID 40109347, 2025). "Assessment indicators included tumour weight and inhibition rate, spleen and thymus indices, serum cytokine levels (IL-2, IL-12, TNF-α, IL-10), as well as the phagocytic rate and phagocytic index of peritoneal macrophages." (PMID 40649307, 2025). "M2TAMs are characterized by the expression of CD68 and CD163 and are known to secrete immunosuppressive cytokines (e.g., IL-10, CCL17, CCL22) that promote angiogenesis, matrix remodeling, and tumor cell migration." (PMID 40281554, 2025). "This adaptive PD-L1 upregulation, in concert with immunosuppressive cytokines IL-10 and TGF-β, orchestrates a profound T-cell exhaustion phenotype and functional impairment within the TME, thereby facilitating immune escape and tumor persistence." (PMID 41007114, 2025). "The modulation of immune responses in cancer by Bregs, through the secretion of immunosuppressive cytokines such as IL-10 and TGF-β, plays a critical role in either dampening or potentiating anti-tumor immunity." (PMID 41285707, 2025). "The tumor microenvironment (TME), including monocytes, Myeloid-Derived Suppressor Cells (MDSCs), and immunosuppressive cytokines such as TGF-β, IL-10, and PGE2, helps induce and maintain split anergy." (PMID 41008790, 2025). "While M1-polarized TAMs exhibit antitumor activity, M2-polarized TAMs dominate the HNSCC microenvironment, promoting tumor progression via ARG1-mediated L-arginine depletion (impairing TCR signaling) and IL-10/VEGF-driven immunosuppressive angiogenesis." (PMID 40438103, 2025). "Through suppression of the HMGB1/TLR4 axis, AS-IV reduced M2 macrophage-mediated production of pro-tumor factors such as TGF-β, matrix metalloproteinase 9 (MMP-9), and IL-10." (PMID 40417220, 2025). "MiR-21 influences this process by upregulating M2 markers (like CD206 and IL-10) and downregulating M1 markers (such as TNF-α and iNOS), thus driving macrophages toward the tumor-promoting M2 phenotype." (PMID 40330466, 2025). "M2 TAMs secrete IL-10, CCL17/22, and VEGF, while activating PI3K/AKT and STAT3 pathways in tumor cells, which promotes proliferation and immune evasion." (PMID 40963620, 2025). "In vivo studies showed that treatment with BB-NVs increased the proportion of CD3+CD4+ and CD3+CD8+ cells in tumor tissue and spleen and significantly increased the expression of anti-tumor cytokines TNF-α, IL-6, IL-10, and IFN-γ." (PMID 40284501, 2025). "Such cells secrete a variety of cytokines that suppress immune responses including TGF-β, IL-10, and VEGF, which collectively contribute to immune evasion and tumor progression." (PMID 41357575, 2025). "Their cytotoxic activity is dampened by immune checkpoint signaling, particularly through the PD-1/PD-L1 axis, and by inhibitory factors secreted by tumor cells, such as TGF-β and IL-10." (PMID 40866941, 2025). "In vivo, S1-driven tumor suppression correlated with significant remodeling of the tumor microenvironment, marked by reduced levels of immunosuppressive cytokines (TGF-β, IL-6, IL-10) and increased infiltration of TAMs." (PMID 40507880, 2025).
tumor (continued). "Correspondingly, the mRNA levels of the cytokine and chemokine were significantly higher in 4KO-LLT1 CAR-T cells stimulated with tumor cells than in 4KO CAR-T cells, with IL-10 showing the most pronounced fold-change." (PMID 39856752, 2025). "These M2 macrophages, in turn, secrete anti-inflammatory and tumor-promoting factors like IL-10 and TGF-β, further enhancing cancer cell invasion, metastasis, and immune evasion, thereby creating a tumor-promoting microenvironment." (PMID 40330466, 2025). "Meanwhile, their action can also be impaired by tumor-secreted biomolecules, such as TGF-β, PD-L1, and IL-10, as well as under hypoxic conditions." (PMID 41369383, 2025). "The inhibitory effect of TAMs can be exerted through the secretion of cytokines, such as IL-10 and TGF-β, which form a complex network to suppress T cell activity and impair T cells’ anti-tumor capabilities." (PMID 40079015, 2025). "In contrast, the anti-inflammatory cytokine IL-10 suppresses VEGF production from macrophages and tumor cells and inhibits VEGF-dependent endothelial proliferation." (PMID 41583457, 2025). "Prolonged IL-10’s half-life and well-tolerated.Targeted EGFR-positive tumors.Improved tumor-specific cytotoxic activity of CD8+ T cells.Hindered DC-mediated apoptosis of CD8+ TILs.Overcame resistance to ICIs therapy." (PMID 40149345, 2025). "Sleep fragmentation-induced IL-10 secretion further reinforces an immunosuppressive TME, potentially facilitating tumor progression by inhibiting effective anti-tumor immune responses." (PMID 41357522, 2025). "Intrinsic to the success of CAR therapy is the activation of the immune system via cytokines such as IL-1, IL-6, IL-10, TNF-a, and interferon (IFN)-g to kill tumor cells." (PMID 40264764, 2025). "Even more cunningly, tumor cells secrete various immunosuppressive cytokines, such as transforming growth factor-β (TGF-β) and interleukin-10 (IL-10), creating an immunosuppressive atmosphere in the tumor microenvironment (TME)." (PMID 41415289, 2025). "These TAMs release IL-10 and TGF-β, further suppressing CD8+ T-cell activation and fostering a tumor-permissive immune microenvironment." (PMID 41488634, 2025). "The S1, S5, and S6 treatment groups showed enhanced anti-tumor immunity, with reduced TGF-β, IL-6, and IL-10 levels." (PMID 40507880, 2025). "TAMs in ascites facilitate tumor progression via ECM degradation, angiogenesis, and immune evasion through cytokine secretion such as IL-10 and TGF-β." (PMID 40075635, 2025). "While IL-10’s immunosuppressive actions in the TME contribute to immune evasion, it is important to consider that IL-10 can also be anti-tumor under certain situations." (PMID 40739089, 2025). "Further, TIM-3+ Treg cells have enhanced suppressive function and increased expression of IL-10, and mice with enforced expression of TIM-3 on Treg cells show impaired anti-tumor immunity and increased tumor growth." (PMID 40468052, 2025). "g., EGF, TGF-β, IL-10) and express surface markers such as CD163 and CD206, which are involved in anti-inflammatory effects, tissue repair, tumor promotion, and immune regulation." (PMID 40766304, 2025). "This cascade upregulates IL-10 and immune checkpoint molecules, reducing infiltration of CD8+ T cells while increasing regulatory T cells, thereby promoting an immunosuppressive tumor microenvironment that supports tumor progression." (PMID 40924302, 2025). "The study examines the relationship between cytokines and tumor microenvironment (TME), revealing the role of immunosuppressive cytokines like IL-10 and transforming growth factor-beta (TGF-β) in promoting an immune-evasive phenotype." (PMID 40309351, 2025). "A major mechanism through which TANs dampen anti-tumor immunity is the release of various substances, including TGF-β, IL-10, and ROS." (PMID 40486614, 2025). "IL10 and IL35 produced by regulatory B cells seem to be the two cytokines responsible for tumour proliferation and T‐cell suppression." (PMID 40831074, 2025).
tumor (continued). "M2 macrophages, cellular immune components of the TME, usually secrete immunosuppressive cytokines such as IL-10 and TGF-β, which promote tumor growth and immune escape." (PMID 40833956, 2025). "Known for its role in aggressive cancers, TIMP1 promotes macrophage polarization via IL-10 and TGF-β secretion, enhancing tumor progression through the PI3K/AKT pathway." (PMID 40299331, 2025). "These cells can inhibit T cell activity by secreting immunosuppressive molecules, such as IL-10 (interleukin 10) and TGF-β (transforming growth factor beta), which hinder the effective elimination of tumor cells by T cells." (PMID 40612869, 2025). "Their maturation and functional abilities are hampered by factors generated by the tumor microenvironment, including VEGF and IL-10, which lead to poor T cell priming and the formation of immunological tolerance." (PMID 41550427, 2025). "They release immunosuppressive cytokines such as IL-10, IL-4, IL-13, IDO and TGF-β, reducing TNFα and INF-γ levels in effector CD4+ T cells, inhibiting APCs function, and downregulating tumor-specific cytotoxicity within the immune response." (PMID 41208963, 2025). "M2d macrophages are activated by TLR antagonists, IL-6, and adenosine, with adenosine promoting the expression of IL-10 and VEGF, thereby exacerbating angiogenesis and tumor progression." (PMID 40375990, 2025). "These cells secrete immunosuppressive cytokines (IL-10, TGF-β) and reactive oxygen species (ROS), enhancing tumor invasiveness and shaping a pro-tumor inflammatory milieu." (PMID 41373809, 2025). "IL-10 can inhibit the cytotoxic function of CD8 + T cells, help tumor cells evade immune surveillance, and promote the immunosuppressive state of the tumor microenvironment." (PMID 41488073, 2025). "IL-10 can reduce the expression of MHC class II molecules on antigen-presenting cells, hindering the presentation of tumor antigens to T cells." (PMID 40636453, 2025). "Six overlapping hub genes (CD8A, CDC20, E2F1, IL10, TNF, VCAM1) were overexpressed in GS 10 tumors, reflecting key pathways in tumor progression." (PMID 40227503, 2025). "The M2 macrophages secrete immunosuppressive cytokines like IL-10 and TGF-β, which inhibit effective anti-tumor immune responses." (PMID 39869563, 2025). "On the other hand, M2 macrophages secrete anti-inflammatory cytokines such as IL-10 and TGF-β that promote tissue repair, angiogenesis, and tumor progression." (PMID 40895532, 2025). "M2 TAMs create a pro-tumorigenic environment by secreting cytokines like IL-10 and TGF-β, inhibiting the activation of cytotoxic T-cells and promoting tumor growth and metastasis." (PMID 40281554, 2025). "Tumor-derived lactate drives transcriptional reprogramming (CCL2, ARG1, IL10, S100A9) in TAMs via the ENSA-K63la/STAT3-pY705 axis, promoting an immunosuppressive environment and immunotherapy resistance." (PMID 39883522, 2025). "Cancer cells, in turn, influence DC maturation via IL-10 or VEGF, while immature DCs facilitate tumor proliferation by inducing antigen tolerance." (PMID 40136652, 2025). "Cytokines secreted by tumor cells and Th2 lymphocytes (such as IL-4, IL-10, and TGF-β) drive the polarization of TAMs toward the M2 phenotype, resulting in immune suppression and accelerated tumor development." (PMID 40843751, 2025). "Tumor cells and stromal components secrete immunosuppressive factors such as VEGF, IL-10, TGF-β, PGE2, and IDO, which inhibit DC maturation and promote tolerogenic phenotypes." (PMID 40825677, 2025). "TH2 cells secrete IL4, IL5, IL10, IL13, and IL17 - all of which have been shown to contribute to the tumor-promoting role of this subtype, even though IL4, IL5, and IL13 have been shown to contribute to the growth and metastasis of cancer." (PMID 41019045, 2025). "They secrete the Interleukins (IL-) IL-4, IL-6, IL-8, and IL-10, TGF-β (Transforming Growth Factor), EGF (Epidermal Growth Factor), and other factors that facilitate tumour growth and cell migration." (PMID 41009413, 2025).